NF2 (NF2, moesin-ezrin-radixin like (MERLIN) tumor suppressor)
Description:
Probable regulator of the Hippo/SWH (Sav/Wts/Hpo) signaling pathway, a signaling pathway that plays a pivotal role in tumor suppression by restricting proliferation and promoting apoptosis. Along with WWC1 can synergistically induce the phosphorylation of LATS1 and LATS2 and can probably function in the regulation of the Hippo/SWH (Sav/Wts/Hpo) signaling pathway. May act as a membrane stabilizing protein. May inhibit PI3 kinase by binding to AGAP2 and impairing its stimulating activity. Suppresses cell proliferation and tumorigenesis by inhibiting the CUL4A-RBX1-DDB1-VprBP/DCAF1 E3 ubiquitin-protein ligase complex.
Synonyms: SCH; merlin; ACN; BANF; merlin-1; SWNV
Tractability: Small molecule: a structure with a bound ligand is known; it has a high-quality binding pocket. Antibody: its Gene Ontology location is reachable by antibodies, with high confidence; UniProt places it where antibodies can reach, with medium confidence; the Human Protein Atlas places it where antibodies can reach. PROTAC: UniProt records ubiquitination sites on it; ubiquitination databases record sites on it; its protein half-life has been measured.
Gene: Protein-coding gene on chromosome 22 (29,603,546 to 29,698,598, forward strand). Ensembl gene ENSG00000186575.
Subcellular location: Cell projection, filopodium membrane (Isoform 1); Cell projection, ruffle membrane; Nucleus; Cytoplasm, perinuclear region (Isoform 7); Cytoplasmic granule; Cytoplasm, perinuclear region (Isoform 9); Nucleus (Isoform 10); Cell projection, filopodium membrane; Cytoplasm, perinuclear region; Cytoplasm, cytoskeleton
Subcellular location (Human Protein Atlas): Plasma membrane; Cytosol; Nucleoplasm
Pathways (Reactome):
Immune System: Regulation of actin dynamics for phagocytic cup formation
Signal Transduction: RHO GTPases activate PAKs
Gene Ontology:
Molecular function: protein binding; signaling adaptor activity; actin binding; integrin binding; cytoskeletal protein binding
Biological process: actin cytoskeleton organization; hippo signaling; negative regulation of cell population proliferation; negative regulation of cell-cell adhesion; negative regulation of receptor signaling pathway via JAK-STAT; positive regulation of stress fiber assembly; regulation of apoptotic process; regulation of cell cycle; regulation of hippo signaling; Schwann cell proliferation; negative regulation of cell migration; negative regulation of cell-matrix adhesion; positive regulation of early endosome to late endosome transport; positive regulation of protein localization to early endosome; regulation of cell shape; regulation of gliogenesis; regulation of organelle assembly; cell differentiation; lens fiber cell differentiation
Cellular component: cytoplasm; cytosol; early endosome; membrane; nucleolus; nucleoplasm; nucleus; perinuclear region of cytoplasm; plasma membrane; adherens junction; apical part of cell; cytoskeleton; filopodium; cell body; cleavage furrow; cortical actin cytoskeleton; filopodium membrane; lamellipodium; neuron projection; ruffle; ruffle membrane
Genetic constraint (gnomAD): Loss-of-function variants: 8 observed, 77.09 expected, observed/expected ratio (o/e) 0.1, 90% interval 0.06 to 0.19. The upper end of that interval is the gene's LOEUF score, 0.19, which puts it in group 1 of 6, group 1 being the genes least tolerant of losing a copy. Missense variants: 531 observed, 744.11 expected, observed/expected ratio (o/e) 0.71, 90% interval 0.66 to 0.77. Synonymous variants: 266 observed, 270.13 expected, observed/expected ratio (o/e) 0.98, 90% interval 0.89 to 1.09.
Gene-disease validity (ClinGen):
ClinGen rates the evidence that NF2 causes each of these diseases.
NF2-related schwannomatosis (autosomal dominant): Definitive. A tumor-prone disorder characterized by the development of multiple schwannomas and meningiomas.
Cancer hallmarks: invasion and metastasis (suppresses); invasion and metastasis (promotes or suppresses); suppression of growth (promotes); change of cellular energetics (promotes)
Homologues: Orthologues: chimpanzee NF2 (99% identical), macaque NF2 (99% identical), dog NF2 (99% identical), pig NF2 (99% identical), rat Nf2 (99% identical), mouse Nf2 (98% identical), rabbit NF2 (98% identical), guinea pig NF2 (95% identical), zebrafish nf2a (83% identical), tropical clawed frog nf2 (82% identical), Drosophila melanogaster Mer (49% identical), Caenorhabditis elegans nfm-1 (36% identical). Paralogues in human: EZR (46% identical), RDX (46% identical), MSN (44% identical), FRMD4B (24% identical), FRMD4A (22% identical), ERMN (10% identical).
Diseases named in the same sentence as NF2 in open-access papers:
NF2 is named in the same sentence as 326 diseases in open-access papers, as found by Europe PMC text mining. Sharing a sentence is not in itself a finding about the gene and the disease. The quoted sentences say what the papers report.
meningioma (473 papers, 1997 to 2026). A generally slow growing tumor attached to the dura mater. "The brigatinib + INK128 combination exhibits antitumor synergy in both the AG-NF2-Men and Ben-Men-1 meningioma models, suggesting combining brigatinib with mTOR inhibition to more effectively treat NF2-SWN and sporadic NF2-deficient meningiomas." (PMID 41417846, 2026). "We followed a 36-year-old man with an atypical meningioma with somatic NF2 mutation and invasion into the bone, temporalis muscle, and pterygopalatine fossa, treated with surgical resection and adjuvant radiation therapy." (PMID 42088105, 2026). "ONSM represents a predominantly NF2-intact meningioma subtype defined by neural niche-associated transcriptional signatures." (PMID 41622742, 2026). "This study attempted to assess the lipidome profile in meningiomas harboring different NF2 mutation statuses (wildtype and mutated)." (PMID 42096040, 2026). "In comparison, although the tumor-suppressive role of NF2 has been established in mesothelioma, schwannomas, and meningiomas, where it is frequently mutated, the contributions of NF2 inactivation to PDAC development remain elusive." (PMID 41480763, 2026). "NF2 mutations have been well-documented in pediatric meningioma, with reported frequencies ranging from 8% in larger metanalysis to 50% in specialized hubs for concentrated pediatric NF2 care." (PMID 40637916, 2025). "Even low-grade NF2-mutant meningiomas can encase large vessels and cranial nerves, causing debilitating neurological symptoms and relentless recurrence." (PMID 41487565, 2025). "The latest cIMPACT-NOW suggests that histomorphologic CNS WHO Grade 1 meningiomas harboring chromosomal aberrations with 1p deletion and 22q deletion and/or NF2 oncogenic variants should be assigned as Grade 2 meningioma." (PMID 40149634, 2025). "NF2 is an inherited autosomal dominant disorder associated with vestibular schwannoma, meningioma, ependymoma, cataract, lenticular opacities, and retinal hamartomas." (PMID 40713130, 2025). "Due to the frequency of NF2 gene mutations in meningiomas, we expected reduced or lost merlin expression in NF2-mutated meningiomas." (PMID 40447281, 2025). "Clinical studies have indicated that loss-of-function and mutations in the neurofibromin-2 (NF2) gene play a crucial role in promoting meningioma formation." (PMID 39894505, 2025). "Over 80% of sporadic meningiomas fall into one of seven molecular subgroups, including NF2, TRAF7, SMARCB1, KLF4, and mutations in Hedgehog and PI3K pathways." (PMID 40637916, 2025). "The NF2 gene on chromosome 22q is frequently inactivated in meningiomas by loss-of-function events, such as intragenic deletions and truncating mutations, often together with loss of the remaining 22q arm." (PMID 41487565, 2025). "Several studies reported the identification of molecular meningioma subgroups, showing the biallelic mutation of Neurofibromatosis 2 (NF2) as the most common genetic disturbance in meningiomas." (PMID 40562609, 2025). "Our genomic data revealed co-occurrences of non-NF2 mutations in lower-grade meningiomas, suggesting synergistic effects supporting tumour growth." (PMID 40562609, 2025). "TRAF7, SMO, AKT1, and KLF4 mutations, referred to as “non-NF2,” are typically found in lower-grade meningiomas, characterized by fewer chromosomal abnormalities, and generally result in better clinical outcomes." (PMID 40725113, 2025). "Approximately 50–60% of meningiomas harbor NF2 alterations resulting in a two-hit complete loss of function and are implicated in the tumorigenesis of sporadic meningiomas." (PMID 40149634, 2025). "The most prevalent endogenous factor contributing to the development of meningiomas is the NF2 gene mutation." (PMID 39894505, 2025). "Research has revealed that a mutation in NF2 is the most common alteration associated with meningioma oncogenesis." (PMID 40004036, 2025).
meningioma (continued). "VEGF receptor vaccines show potential for NF2-associated schwannomas, but their impact on meningiomas needs further investigation." (PMID 39779595, 2025). "The few studies that have directly assessed VS and meningioma indicate similarities in NF2 gene pathogenic variants and in gene expression related to angiogenesis and tumour suppression (PDGFD, CDH1 and SLIT2)." (PMID 41437121, 2025). "Pediatric meningiomas are often more aggressive, have higher World Health Organization (WHO) grading, have greater association with genetic conditions such as neurofibromatosis type II (NF2), and have a higher risk of recurrence compared to adult meningiomas." (PMID 40637916, 2025). "The NF2 gene, which remains the most common genetic abnormality in sporadic meningiomas, was the first gene to be linked with the meningioma occurrence and is present in up to 69% of malignant meningiomas." (PMID 40075786, 2025). "NF2-driven meningiomas have been associated with a more aggressive histology and earlier recurrence." (PMID 40569492, 2025). "On the one hand, there were five cases of non‐NF2 meningioma displaying a loss of Merlin IHC pattern." (PMID 40815185, 2025). "Bilateral vestibular schwannomas (bVSs), in contrast, are the hallmark lesion for NF2-related schwannomatosis (NF2), a tumor syndrome predisposing one to multiple central nervous system tumors, including schwannomas, meningiomas, and ependymomas." (PMID 39941762, 2025). "It was reported that 32% of mesothelioma patients has somatic NF2 mutation and nearly 50% of meningiomas have allelic losses of NF2." (PMID 41047480, 2025). "NF2 alterations are also associated with an aggressive phenotype of meningiomas, and they were commonly found in high‐grade meningioma." (PMID 40815185, 2025). "Due to the prognostic importance of these mutations and need for objective biomarkers in meningioma diagnostics, it is relevant to identify practical and affordable methods to detect molecular genetic aberrations, such as NF2 gene mutations." (PMID 40447281, 2025). "In this context, meningiomas significantly contribute to morbidity and mortality, reinforcing the need for noninvasive therapies for both NF2-associated and sporadic forms." (PMID 41200151, 2025). "NF2 alterations were detected in 51 cases (46.8%) of all meningiomas: 33 cases with both 22q loss and NF2 mutation, 16 cases with 22q loss only and two cases with NF2 mutation only." (PMID 40815185, 2025). "Notable tumor characteristics included its supratentorial location, high Ki-67 proliferative index, and NF-2 genetic alteration, which are all factors associated with decreased progression-free survival in grade I meningioma patients." (PMID 40918813, 2025). "Based on these findings, cIMPACT‐NOW update 833 proposed that meningioma with 1p deletion combined with 22q loss and/or NF2 oncogenic variants should be graded at least CNS WHO grade 2, even in histologically otherwise benign tumours." (PMID 40815185, 2025). "In meningiomas, NF2 mutations are common, and NF2 loss is associated with increased cell proliferation and tumor growth." (PMID 39712860, 2025). "Meningiomas harboring the NF2 mutation, recorded in numerous cases of metastatic meningioma, appear to have greater genetic instability." (PMID 40725113, 2025). "NF2-associated meningiomas are often managed less aggressively, balancing treatment risks with disease progression." (PMID 39779595, 2025). "NF2 gene aberration (loss of chromosome 22q and/or mutations in NF2) is the most common driver abnormality in meningiomas, which is identified in 40–60% of sporadic meningiomas." (PMID 40815185, 2025). "Meningiomas have 15histologic variants, with NF2-associated types usually of higher grade and convex location." (PMID 41170123, 2025). "In terms of molecular alterations, these meningiomas are associated with HLA locus gain on chromosome 6p and NF2 locus loss paired up with NF2 gene mutations." (PMID 40046333, 2025).
meningioma (continued). "Two pieces of evidence place NF2 mutations at the center of pathogenic drivers in convexity meningiomas." (PMID 40867323, 2025). "The most common genetic abnormality identified in patients with meningioma is the loss of chromosome 22.q12.2, which harbors the neurofibromin-2 gene (NF2)." (PMID 39894505, 2025). "Patients with NF2 are known to be at increased risk for multiple central nervous system tumors, including vestibular schwannomas, meningiomas, and intramedullary tumors (eg, ependymomas), which is why they undergo routine MRI screening of the brain and spine." (PMID 40713130, 2025). "Five cases of non‐NF2 meningioma showed loss of Merlin staining, including three cases of fibrous meningioma, one case of transitional meningioma and one case of meningothelial meningioma." (PMID 40815185, 2025). "Effective implementation of FAK targeted therapy in NF2-mutant meningiomas requires precise diagnostic and stratification strategies." (PMID 41487565, 2025). "The most common molecular alteration in meningioma is the loss of one copy of chromosome 22/alteration of the Neurofibromatosis 2 gene (NF2), both in sporadic meningiomas and those associated with the syndrome of neurofibromatosis type 2." (PMID 41372821, 2025). "NF2, due to NF2 gene mutations, is distinguished by bilateral vestibular schwannomas and the occurrence of other CNS tumors such as meningiomas and ependymomas." (PMID 40427120, 2025). "Type 2 neurofibromatosis (NF2) is recognized as the most common genetic condition associated with meningiomas, with NF2 patients more often developing grade 2 and 3 meningiomas." (PMID 40075786, 2025). "Although reports of NF2 mutations in breast cancer are rare, the inactivation of NF2 in various tumor types, such as meningiomas and mesotheliomas, indicates that this gene plays an important role in tumorigenesis beyond the nervous system." (PMID 39712860, 2025). "In high-grade/progressive meningiomas, the NF2-associated genomic subclass frequently harbors CDKN2A/B alterations." (PMID 41487565, 2025). "While NF2 alterations are frequent in pediatric meningiomas, with a higher frequency of underlying NF2 syndrome, adult-type non-NF2 alterations are typically absent." (PMID 40951339, 2025). "The mutation rates of the TERT promoter and CDKN2A/B in meningiomas are typically less than 5% and are often co-occurring with Neurofibromin 2 (NF2) mutations and/or 22q chromosome deletions." (PMID 40502635, 2025). "For meningiomas with mutations in the Hedgehog (HH) pathway (SMO) or the NF2 pathway (FAK), targeted therapies such as vismodegib (an SMO inhibitor) and GSK2256098 (a FAK inhibitor) are being explored (NCT02523014)." (PMID 40787520, 2025). "Mutations in the neurofibromin 2 (NF2) gene are common, especially in sporadic meningiomas of the fibrous subtype, and are believed to play a pivotal role in tumor initiation." (PMID 41007735, 2025). "In the general population of patients with meningiomas, deletions, nonsense mutations, splice site mutations, and translocations in NF2 are identified in 50–60% of cases." (PMID 39894505, 2025). "Molecular genetic studies into meningioma have identified Neurofibromatosis type 2 (Nf2) as one of the most commonly mutated genes in meningiomas." (PMID 39996452, 2025). "First, roughly 50–75% of NF2 patients develop convexity meningiomas; second, approximately 60% of sporadic convexity meningiomas present with pathogenic variants of NF2." (PMID 40867323, 2025). "A recent review on PIK3CA‐mutated meningiomas underscores that a subset of these tumors, particularly those with non‐NF2 mutations, exhibit estrogen and progesterone receptor positivity and respond aberrantly to hormonal exposure via PIK3CA pathway activation." (PMID 41031251, 2025).